SLC9A5 (solute carrier family 9 member A5)
Description:
Plasma membrane Na(+)/H(+) antiporter. Mediates the electroneutral exchange of intracellular H(+) ions for extracellular Na(+) in 1:1 stoichiometry, thus regulating intracellular pH homeostasis, in particular in neural tissues. Acts as a negative regulator of dendritic spine growth. Plays a role in postsynaptic remodeling and signaling. Can also contribute to organellar pH regulation, with consequences for receptor tyrosine kinase trafficking.
Synonyms: NHE5
Tractability: Small molecule: a high-quality ligand is known. Antibody: UniProt places it where antibodies can reach, with high confidence; its Gene Ontology location is reachable by antibodies, with high confidence; UniProt predicts a signal peptide or a membrane-spanning region; the Human Protein Atlas places it where antibodies can reach. PROTAC: ubiquitination databases record sites on it; a small molecule that binds it is known.
Target class: SLC superfamily of solute carriers; SLC09 family of sodium/hydrogen exchangers; Electrochemical transporter; Transporter
Gene: Protein-coding gene on chromosome 16 (67,237,683 to 67,272,191, forward strand). Ensembl gene ENSG00000135740.
Subcellular location: Cell membrane; Recycling endosome membrane; Cell projection, dendritic spine membrane; Synaptic cell membrane; Cell junction, focal adhesion
Subcellular location (Human Protein Atlas): Cytosol; Plasma membrane
Pathways (Reactome):
Transport of small molecules: Sodium/Proton exchangers
Gene Ontology:
Molecular function: arrestin family protein binding; protein binding; sodium:proton antiporter activity; antiporter activity
Biological process: regulation of intracellular pH; sodium ion transmembrane transport; sodium ion import across plasma membrane; monoatomic cation transport; proton transmembrane transport; regulation of pH; sodium ion transport; transmembrane transport
Cellular component: focal adhesion; neuron spine; plasma membrane; recycling endosome membrane; synapse; synaptic membrane; membrane; dendritic spine membrane
Genetic constraint (gnomAD): Loss-of-function variants: 52 observed, 90.4 expected, observed/expected ratio (o/e) 0.58, 90% interval 0.46 to 0.73. The upper end of that interval is the gene's LOEUF score, 0.73, which puts it in group 2 of 6, group 1 being the genes least tolerant of losing a copy. Missense variants: 871 observed, 1,168.4 expected, observed/expected ratio (o/e) 0.75, 90% interval 0.7 to 0.79. Synonymous variants: 419 observed, 476.03 expected, observed/expected ratio (o/e) 0.88, 90% interval 0.81 to 0.95.
Homologues: Orthologues: chimpanzee SLC9A5 (99% identical), macaque SLC9A5 (99% identical), rat Slc9a5 (95% identical), dog SLC9A5 (95% identical), mouse Slc9a5 (95% identical), rabbit SLC9A5 (95% identical), pig SLC9A5 (95% identical), guinea pig SLC9A5 (84% identical), tropical clawed frog slc9a5 (68% identical), zebrafish slc9a5 (59% identical), Drosophila melanogaster Nhe2 (38% identical), Caenorhabditis elegans nhx-2 (24% identical), and 4 more. Paralogues in human: SLC9A3 (48% identical), SLC9A2 (33% identical), SLC9A1 (31% identical), SLC9A4 (29% identical), SLC9A6 (19% identical), SLC9A7 (19% identical), SLC9A9 (19% identical), SLC9A8 (18% identical), SLC9C1 (14% identical), SLC9C2 (14% identical).
Diseases named in the same sentence as SLC9A5 in open-access papers:
SLC9A5 is named in the same sentence as 11 diseases in open-access papers, as found by Europe PMC text mining. Sharing a sentence is not in itself a finding about the gene and the disease. The quoted sentences say what the papers report.
tumor (3 papers, 2019 to 2022). "Based on CRISPR screen, data mining, and in vivo experiments, we identified and validated three genes (SMAD3, BIRC3, and SLC9A5) able to promote both BRAFi‐resistance and tumor growth." (PMID 33724679, 2021). "Interestingly, we recovered the tumor‐promoting genes SMAD3, BIRC3, and SLC9A5 identified above." (PMID 33724679, 2021).
cancer (2 papers, 2020 to 2021). A tumor composed of atypical neoplastic, often pleomorphic cells that invade other tissues. "The bar plot generated by GEPIA2 clearly showed that the expressions of SLC9A2, SLC9A3, and SLC9A9 in COAD tissues were obviously lower than those in normal tissues, but SLC9A5 and SLC9A7 in cancer were distinctly higher than those in normal tissues." (PMID 34759967, 2021).
SLC9A5 also shares sentences with these, for which no sentence is quoted: glioma (3 papers); Ataxia (1); end-stage renal disease (1); hematological diseases (1); Huntington disease (1); Hypertension (1); infertile (1); melanoma (1); schizophrenia (1).